TXNIP (thioredoxin interacting protein)
Diseases named in the same sentence as TXNIP in open-access papers (continued):
Sharing a sentence is not in itself a finding about the gene and the disease.
atherosclerosis (28 papers, 2013 to 2025). A disease characterized by the build-up of fatty material and calcium deposition in the arterial wall resulting in partial or complete occlusion of the arterial lumen. "TXNIP, linked to oxidative stress, has been associated with diabetic complications and with atherosclerosis; in animal model studies, deletion of TXNIP in atherosclerosis-prone mice was shown to reduce atherosclerosis." (PMID 34081211, 2021). "TXNIP has been linked to atherosclerosis by several in vivo and in vitro studies 50,69." (PMID 25754218, 2015). "Overexpression of miR-194-3p enhances the proliferation of ECs and inhibits apoptosis in atherosclerosis, and the knockdown of TXNIP can alleviate atherosclerosis." (PMID 40563948, 2025). "In summary, we show that endothelial c-REL orchestrates the initiation of atherosclerosis at sites of disturbed flow by activating a TXNIP-p38 pathway leading to inflammation and a NF-κB2-p21 pathway driving proliferation." (PMID 39982773, 2025). "This role of GAS5 in atherosclerosis progression is further supported by a study investigating the role of GAS5 in coronary AS through the miR-194-3p/Thioredoxin-interacting protein (TXNIP) axis." (PMID 39941145, 2025). "The present study demonstrates that AT-I protects against nicotine-induced macrophage pyroptosis and atherosclerosis by inhibiting the TLR4/ROS/TXNIP/NLRP3 signaling pathway." (PMID 40422906, 2025). "Diabetic individuals, who also are more prone to atherosclerosis, demonstrate higher TXNIP expression levels." (PMID 36465470, 2022). "The findings suggest that TXNIP plays a key role in the development of oxidation, inflammation, and atherosclerosis in mice." (PMID 36588561, 2022). "Even if the endothelial levels of TXNIP are correlated with the adhesion of leucocytes, TXNIP levels in leucocytes also have an impact on the physiopathology of atherosclerosis." (PMID 33567593, 2021). "All these findings validate the crucial role of SNP rs7212 and TXNIP protein in the development of atherosclerosis, and the detailed mechanism needs to be elucidated in future studies." (PMID 27470124, 2016). "The atheroprotective effect of TXNIP ablation implicates that modulation of TXNIP expression may serve as a potential target for intervention of atherosclerosis and inflammatory vascular disease." (PMID 35771146, 2022). "Intervention of TXNIP expression may be a potential target for the prevention and treatment of atherosclerosis and inflammatory vascular diseases." (PMID 36588561, 2022). "However, further studies are necessary to investigate the causal relationship between exercise training and ER stress-induced TXNIP/NLRP3 inflammasome signaling in coronary arterioles in atherosclerosis." (PMID 34326395, 2021). "Recent studies have shown that TXNIP promoted endothelial inflammation and increased leucocyte adhesion to endothelial cells under conditions of disturbed blood flow that characterize blood vessel regions prone to atherosclerosis." (PMID 25754218, 2015). "Thus, our work could help to clarify the role of TXNIP in the pathological process of atherosclerosis and open up a new insight into the regulatory mechanism of VSMCs calcification in combating plaque rupture by galectin-3." (PMID 35771146, 2022). "More specifically, TXNIP mRNA levels in leucocytes have also been investigated and are increased in patients with unstable angina pectoris or with acute myocardial infarction, suggesting the role of TXNIP in atherosclerosis and the pathogenesis of cardiovascular diseases." (PMID 33567593, 2021). "Hence, TXNIP inhibitors also appear as a valuable therapeutic option in atherosclerosis." (PMID 35008500, 2021). "Taken together, these results suggest that vulnerable psEVs promote endothelial inflammation and atherosclerosis partially through miR‐497‐5p delivery and UCP2 suppression to modulate the ROS/TXNIP/NLRP3 pathway." (PMID 40391195, 2025).
atherosclerosis (continued). "Thioredoxin-interacting protein (TXNIP) inflammasome-mediated inflammation in macrophages has an important role in various cardiovascular diseases, including AAA and atherosclerosis." (PMID 35883151, 2022). "In addition, activation of TXNIP in the CVD system induces hypertension, atherosclerosis, arterial stiffness and CKD28,29." (PMID 40610750, 2025). "Finally, mechanistic investigations revealed that vulnerable psEVs promoted endothelial inflammation and atherosclerosis partially through miR‐497‐5p delivery and UCP2 suppression to activate the ROS/TXNIP/NLRP3 pathway." (PMID 40391195, 2025). "Also, we determine more in-depth underlying molecular mechanisms by which exercise training improves coronary endothelial function by regulating ER stress, TXNIP/NLRP3 inflammasome signaling cascades, and UCP2-regulated ROS generation in atherosclerosis." (PMID 34326395, 2021). "However, little is known about the mechanistic link between ER stress, TXNIP/NLRP3 inflammasome activation, and UCP2 activity on coronary vascular dysfunction in atherosclerosis." (PMID 34326395, 2021). "In addition, Metformin was shown to inhibit NLRP3 inflammasome activation, and suppressed atherosclerosis in ApoE−/− mice, at least partially through activation of AMPK and regulation of Trx-1/TxNIP." (PMID 35008500, 2021). "Endothelial cells of LIMA, which are not prone to atherosclerosis, stained neither for TXNIP nor for p21." (PMID 25754218, 2015). "Furthermore, we demonstrated that vulnerable psEVs promoted endothelial inflammation and atherosclerosis, partially through the delivery of miR‐497‐5p and subsequent suppression of UCP2, thereby activating the ROS/TXNIP/NLRP3 pathway, a well‐established mechanism of NLRP3 activation." (PMID 40391195, 2025). "Thioredoxin interacting protein (TXNIP) is a regulatory protein involved in oxidative stress, which can inhibit the thioredoxin (TRX) antioxidant system and participate in the occurrence of oxidative stress in many diseases such as ischemia-reperfusion injury, acute lung injury, and atherosclerosis." (PMID 34804174, 2021). "No staining of TXNIP or p21 was observed in Factor VIII-positive cells from sections of LIMA, which are resistant to cholesterol buildup and atherosclerosis 61,62." (PMID 25754218, 2015).
diabetic retinopathy (28 papers, 2012 to 2025). "In a model of diabetic retinopathy, enhanced expression of thioredoxin‐interacting protein (TXNIP) induces oxidative stress, DNA damage and pericyte loss." (PMID 40309782, 2025). "TXNIP overexpression causes an unbalance of these biological processes, which have been known as important contributors to the emergence of multiple diabetic complications, including diabetic retinopathy and diabetic nephropathy." (PMID 30733849, 2019). "According to recent researches, TXNIP participated in the ferroptosis of frucose-induced renal injury, diabetic retinopathy, and multiple sclerosis." (PMID 40388874, 2025). "In diabetic retinopathy, TXNIP was reported to regulate the autophagy and apoptosis of Müller cells via the PI3K/Akt/mTOR signaling pathway." (PMID 39736512, 2024). "In conclusion, ACT inhibits Müller cell reactive proliferation and alleviates diabetic retinopathy by regulating TXNIP and mediating the expression of Kir4.1 channels in a PI3K/Akt-dependent manner." (PMID 39689088, 2024). "Chronic hyperglycemia-induced thioredoxin-interacting protein (TXNIP) expression, associated oxidative/nitrosative stress (ROS/RNS), and mitochondrial dysfunction play critical roles in the etiology of diabetic retinopathy (DR)." (PMID 34940029, 2021). "TXNIP has been associated with ROS/RNS stress, mitochondrial dysfunction, inflammation, and premature cell death in diabetic retinopathy." (PMID 32397116, 2020). "Thioredoxin-interacting protein (TXNIP), an endogenous inhibitor of thioredoxin, has been shown to be associated with diabetic retinopathy and nephropathy." (PMID 30733849, 2019). "This role for TXNIP in the development of diabetic retinopathy and nephropathy has been shown to be involved in NLRP3 inflammasome activation and release of IL-1β." (PMID 30733849, 2019). "Thioredoxin-interacting protein (TXNIP) plays a critical role in oxidative stress, inflammation, apoptosis and the pathogenesis of diabetic retinopathy (DR)." (PMID 31023645, 2019). "Similarly, TIL has been shown to reduce inflammatory responses in diabetic retinopathy through the Nrf2/TXNIP/NLRP3 inflammasome pathway." (PMID 39388398, 2024). "TXNIP binds to thioredoxin (Trx) inhibiting its ability to neutralise oxidants, and prolonged overexpression of TXNIP has been shown to lead to premature cell death in diabetic retinopathy." (PMID 38574408, 2024). "The level of TXNIP was also demonstrated to be highly up-regulated in diabetic retinopathy." (PMID 36837498, 2023). "Experimental models of diabetic retinopathy have shown that silencing thioredoxin interacting protein TXNIP prevents epigenetic modifications in the promoter of cyclooxygenase 2 (Cox2), an enzyme important in the synthesis of a major mediator of inflammation, prostaglandin E2 (PGE2)." (PMID 36672234, 2023). "miRNA miR-590-3p, which has been proved to play an active role in inflammation, could directly target NLRP1 and NOX4 and inhibit pyroptosis in diabetic retinopathy through the NOX4/ROS/TXNIP/NLRP3 pathway." (PMID 35957838, 2022). "Thus, TXNIP represents a promising new therapeutic target for many pathologies related to metabolic diseases, including diabetic retinopathy and retinal neurodegenerative diseases." (PMID 30140371, 2018). "TXNIP is a potential target to ameliorate blinding ocular complications of diabetic retinopathy." (PMID 22474421, 2012). "Melatonin could also control diabetic retinopathy via inhibiting expressions of TXNIP." (PMID 35624485, 2022). "IRE1α may exacerbate diabetic retinopathy because it is known to get hyperactivated during the hyperglycemic condition and may degrade the miRNAs and increase the stability of a pro-oxidant and pro-apoptotic TXNIP." (PMID 32397116, 2020). "Thioredoxin-interacting protein (TXNIP) is involved in oxidative stress and apoptosis in diabetic retinopathy." (PMID 28492550, 2017).
lung carcinoma (27 papers, 2013 to 2025). "In contrast, loss of TXNIP facilitates rapid cell division and activation of DNA replication, leading to cell proliferation in breast and lung cancer models." (PMID 37794178, 2023). "Accordingly, it is conceivable that low TXNIP expression is an independent risk factor and leads to a poor prognosis in breast, bladder, and lung cancer patients." (PMID 35843949, 2022). "Studies have also noted that lung cancer patients with high levels of TXNIP expression had reduced rates of progression-free survival." (PMID 40182050, 2025). "The results showed that the expression of TXN and TXNRD1 was higher in most lung cancer cell lines than in the normal lung epithelial cell line Beas-2b, while the opposite was observed for TXNIP." (PMID 39744566, 2025). "The tumor-suppressive mechanism of TXNIP in lung cancer is likely attributed to its promotion of A2BR degradation and inhibition of cRaf/Erk signaling." (PMID 40182050, 2025). "For example, lung cancer patients with high levels of TXNIP exhibit decreased progression-free survival compared to counterparts with low TXNIP levels (18.0 vs. 23.0 months)." (PMID 37794178, 2023). "Combining a TXNIP agonist, D-Allose, with chemotherapy or radiotherapy results in enhanced antitumor effects in both head and neck and lung cancer models." (PMID 37794178, 2023). "TXNIP expression, on the other hand, is increased in lung cancer cells by inhibiting activated PI3K/Akt signaling." (PMID 36366411, 2022). "In the present study, we revealed for the first time that both E6 and E7 proteins in lung cancer cells induced the loss of PTEN activity and decreased the expression of TXNIP as well." (PMID 33282728, 2020). "In the present study, we validated that the inhibition of TXNIP significantly promoted the glucose uptake by GLUT1 in lung cancer cells." (PMID 33282728, 2020). "Our results demonstrated that the overexpression of both E6 and E7 significantly downregulated the expression of p-PTEN at S380 and the knockdown of PTEN decreased the expression of TXNIP in lung cancer cells." (PMID 33282728, 2020). "It has been shown that using tyrosine kinase inhibitor (TKIs) to inhibit PI3K/Akt signaling in NSCLC cell lines can lead to a decrease in cell membrane-localized GLUT1, but increases in TXNIP expression in lung cancer tissues." (PMID 33194655, 2020). "In lung cancer cells, TXNIP regulates NaBu- instead of 4PBA-induced H4K5 acetylation and H3K4 trimethylation by increasing the expression of WDR5 after which there is an increase in the activation of caspase 3/7 and cell death." (PMID 33194655, 2020). "Thioredoxin interaction protein (TXNIP) has pivotal roles in prostate cancer, lung cancer, and breast cancer, and has an especially prognostic effect in NSCLC." (PMID 30390072, 2019). "Conversely, a recent report on lung cancer patients demonstrated that TXNIP was hypoxia inducible in lung cancer cell lines and that patients with high levels of TXNIP had significantly shorter PFS which was maintained in a multivariate analysis." (PMID 30479697, 2018). "Additionally, other ferroptosis-related molecules, such as NCOA4 (nuclear receptor coactivator 4) and TXNIP (thioredoxin-interacting protein), also play important roles in ferroptosis in lung cancer." (PMID 39917300, 2025). "For example, miR-224 has a tumor-promoting effect in nonsmall cell lung cancer, pancreatic cancer, and cervical cancer via targeting of homeobox D10 (HOXD10), androgen receptors, thioredoxin-interacting protein (TXNIP), and Ras-association domain family 8 (RASSF8)." (PMID 37534255, 2023). "It has recently been demonstrated that administering tyrosine kinase inhibitors (TKIs) to block PI3K/Akt signaling can significantly reduce the amount of GLUT1 that is bound to the cell membrane, despite increasing the synthesis of TXNIP in lung cancer tissues." (PMID 36366411, 2022). "Furthermore, circDCUN1D4 suppressed metastasis and glycolysis of lung cancer cells in a TXNIP-dependent manner." (PMID 33425493, 2021).
lung carcinoma (continued). "Our findings provided new evidence in support of the critical role of TXNIP in the pathogenesis of HPV-related lung cancer, and might also suggest novel therapeutic targets." (PMID 33282728, 2020). "The inhibition of TXNIP also promoted the glucose uptake by GLUT1 in lung cancer cells." (PMID 33282728, 2020). "However, the crosstalk between TRAF6 and TXNIP in non‐small cell lung cancer (NSCLC) is currently unclear." (PMID 31578830, 2020). "The present study also indicated that the relative mechanisms of SLC34A2 in A549 lung cancer may be associated with the activation of the complement alternative pathway (C3 and C4b) and upregulation of the expression of SELENBP1, TXNIP, PDZK1IP1 and DUSP6." (PMID 25017204, 2014). "Finally, it was recently documented that in A549 human lung cancer cells where TXNIP expression was down-regulated there was a promotion of the epithelial-mesenchymal transition." (PMID 24376827, 2013). "In wild-type chemosensitive lung cancer or pancreatic cancer cells, cytotoxic drugs increase sphingomyelinase activity, thus enabling hydrolysis of sphingomyelin to ceramide, increasing ROS production, and leading to the release of thioredoxin-interacting protein (TXNIP) from thioredoxin." (PMID 37381723, 2023). "LHFPL-AS2, a tumor-suppressive lncRNA in lung cancer, is downregulated under hypoxia due to the reduction in EGR1 expression, resulting in the transcriptional repression of thioredoxin-interacting protein (TXNIP) and promoting tumor metastasis." (PMID 35625948, 2022). "However, the PTEN-mediated regulation of TXNIP in lung cancer remains unknown." (PMID 33282728, 2020). "The aim of current study was to elucidate the regulatory mechanism between HPV16E6/E7, PTEN, TXNIP, HIF-1α, and GLUT1 in lung cancer cells and provide a new strategy for the treatment of HPV-related lung cancer." (PMID 33282728, 2020). "Our results provided new molecular mechanisms in HPV16 E6/E7 promoted the glucose uptake by relieving TXNIP inhibitory effect on HIF-1α and GLUT1 in lung cancer cells." (PMID 33282728, 2020). "TNF receptor‐associated factor 6 (TRAF6) promotes the development of human lung cancer through bridging RAS and NF‐kB pathways; on the other hand, thioredoxin‐interacting protein (TXNIP) suppresses the growth of tumors." (PMID 31578830, 2020). "As a suppressor gene in lung cancer, TXNIP is also confirmed to be a target of miR-411-5p and decreased in NSCLC cell lines and lung cancer tissue samples." (PMID 30390072, 2019). "In a lung cancer cell, H4K5 acetylation and H3K4 trimethylation induced by sodium 4-phenylbutyrate (4PBA) were replaced by TXNIP-dependent sodium butyrate (NaBu) as they promote the WDR5 expression leading to the initiation of caspase 3/7 and induction of apoptosis." (PMID 36366411, 2022). "Collectively, these results suggest that miR-411-5p/3p are required for NSCLC development by suppressing SPRY4 and TXNIP; thus, the miR-411-SPRY4-AKT axis might act as a promising target for lung cancer therapy clinically." (PMID 30390072, 2019).